JAK1 (Janus kinase 1)
Diseases named in the same sentence as JAK1 in open-access papers (continued):
Sharing a sentence is not in itself a finding about the gene and the disease.
colon carcinoma (15 papers, 2002 to 2023). "The increased expression of METTL3, which mediates m6A modification on JAK1 mRNA, is shown to be correlated with a poor prognosis in colon cancer patients." (PMID 37568073, 2023). "In mice with 1,2-dimethylhydrazine-induced colon cancer, the amelioration of colon cancer in mice by inulin involved modulation of Janus kinase-1/β-catenin signaling." (PMID 37638034, 2023). "For this reason, we performed in vitro studies in colon cancer cells (SW-620) treated with RE to confirm and validate the specific effect of RE on decreasing the expression levels of JAK1, NFE2L2, CHKA, and BMP2 genes." (PMID 31450563, 2019). "Among the deregulated genes involved in the EMT signaling, CTNNB1, as well as JAK1 play key roles in colon cancer progression: CTNNB1 through the activation of Wnt/β-catenin signaling, and JAK/STAT pathway by regulating cell survival and proliferation, differentiation and migration." (PMID 32107391, 2020). "Notably, colon cancer cells can evade JAK2/JAK1-targeted therapy by a reversible shift of the RAS-MEK-ERK pathway activity, which explains the treatment failure of JAK1/2 inhibitors in refractory CRC." (PMID 30670049, 2019). "In summary, this study showed that fasting could induce autophagy of colon cancer cells and then downregulate the level of adenosine, which increased M2 polarization of TAMs through inactivating JAK1/STAT3, and eventually inhibitted tumor growth by promoting antitumor immunity in vitro and in vivo." (PMID 29088814, 2017). "Butyrate reduced JAK2 phosphorylation, JAK1 phosphorylation, STAT1 phosphorylation and its nuclear translocation and DNA binding activity in IFN-γ-activated HCT116 or Hke-3 colon carcinoma cell lines." (PMID 35409339, 2022). "GO enrichment analysis showed that specific proteins, including TGFβ1, adenomatous polyposis coli (APC), CTNB1, low-density lipoprotein receptor-related protein (LRP) 5 (LRP5), LRP6, JAK1, ST14, and TP53BP1, were hypothetical CD151-interacting proteins in colon cancer." (PMID 33767593, 2021).
multiple myeloma (15 papers, 2014 to 2025). "JAK kinases, mainly JAK1 and JAK2, have been found to participate in the pathogenesis of multiple myeloma, a malignancy susceptible to Bortezomib that can develop resistance as well." (PMID 40699751, 2025). "Preclinical study in multiple myeloma models revealed that FT suppressed the STAT3/5-DNA binding capacity while simultaneously inhibiting the activation of upstream kinases JAK1, JAK2 and Src." (PMID 40841966, 2025). "IL-21 was originally demonstrated to be a growth and survival factor in human myeloma cell lines, which was mediated through the activation of JAK1/STAT3 signaling." (PMID 38720319, 2024). "IL-21 was originally demonstrated to be a growth and survival factor in human myeloma cell lines, which is mediated through the activation of the JAK1/STAT3 signaling." (PMID 38720319, 2024). "It impaired the advancement of multiple myeloma xenograft tumors in male thymic mice by suppressing STAT3 activation by inactivating JAK1 and c-Srcin in various preclinical cancer models." (PMID 32545187, 2020). "• IFNα-induced apoptosis of multiple myeloma cells depends on Jak1 and Bim." (PMID 26405162, 2015). "Importantly, the JAK1/STAT3 pathway was previously shown to alter proteasome inhibitor sensitivity in multiple myeloma, and therefore could possibly induce bortezomib resistance in the case of TKI-resistant CML." (PMID 33712704, 2021). "A study demonstrated that crocin can mediate the suppression of STAT3 and inhibit the upstream kinases JAK1, JAK2, and SRC, thereby preventing the progression of multiple myeloma." (PMID 40841966, 2025). "Leelamine from pine’s bark attenuated phosphorylation of upstream JAK1/JAK2/Scr macromolecules and downstream STAT3, hence evoking myeloma cell cycle arrest and apoptosis." (PMID 34680295, 2021). "In human multiple myeloma (MM) cells, constitutive and IL-6 inducible STAT3 activation are inhibited by inhibiting tyrosine kinases such as JAK1 and JAK2." (PMID 34539403, 2021). "In multiple myeloma cells, it restrained the constitutive and IL-6-induced activation of STAT3 through inactivation of JAK1 and c-Src in a concentration-dependent fashion." (PMID 32545187, 2020). "The analysis of the whole transcriptome data revealed different expression levels of several genes, such as JAK1, JAK2, JAK3, RAF, IL6R, NCAM (CD56), WHSC1, MCL1, BCL2, and IGF1, which showed myeloma pathogenesis." (PMID 30079703, 2019). "A research study reported that the inhibition of the activation of upstream JAK1, JAK2, and c-Src kinases suppressed the downstream STAT3 in human multiple myeloma cells." (PMID 25405202, 2014). "Using the 6G4 anti‐JAK1 antibody no JAK1 expression was observed on the BM myeloma cells or on the BM microenvironment (data not shown)." (PMID 32628819, 2020). "We further examined whether tubulosine could affect IFN‐α‐induced JAK1‐ and/or TYK‐2 signalling in multiple myeloma U266 cells." (PMID 32558259, 2020). "For all the 99 myeloma cases, JAK1 was negative regardless of neoplastic and mesenchymal cells." (PMID 32628819, 2020).
bladder cancer (14 papers, 2012 to 2025). "We recently identified germline loss of function mutations in Janus Associated Kinase 1 (JAK1) causing primary immunodeficiency characterized by infections and associated with early onset, fatal high-grade bladder carcinoma." (PMID 31552026, 2019). "The absence of an immune infiltrate observed in the patient's tumor by immunohistochemistry supports our conclusion that loss of JAK1 in bladder cancer cells results in a poorly immunogenic tumor." (PMID 31552026, 2019). "While our patient remains the only reported individual with partial JAK1 deficiency caused by germline loss of function mutations, somatic variants in JAK1 have been described in other patients with very high-risk bladder cancer." (PMID 31552026, 2019). "Here, we report the identification of germline JAK1 mutations that result in a functional JAK1 deficiency associated with susceptibility to atypical mycobacterial infection and early-onset bladder carcinoma." (PMID 28008925, 2016). "We recently reported the first case of germline loss of function mutations causing partial JAK1 deficiency in humans which resulted in immunodeficiency characterized by mycobacterial infection, suggesting a dominant effect on the IFNγ pathway, and high-grade bladder carcinoma." (PMID 31552026, 2019). "The early-onset and aggressive nature of the malignancy, along with the fact that JAK1 is a hotspot for damaging somatic mutations in bladder carcinoma, led us to investigate whether impaired JAK1 function may be a specific predisposing factor for urothelial carcinoma." (PMID 31552026, 2019). "Mechanistically, antitumor effects on bladder cancer cells were noted following treatment of berberine, exerted by inhibiting Janus kinase 1- STAT 3 signaling via miR-17-5p upregulation." (PMID 36144625, 2022). "Together, our findings support a role for urothelial cell JAK1 in immune surveillance and development of bladder cancer." (PMID 31552026, 2019). "Our findings provide new insight into immune and intrinsic signaling regulation of urothelial cells and support a role for JAK1 in the pathogenesis of bladder cancer." (PMID 31552026, 2019). "As expected, the expression of MTHFD2 correlated positively with the expression of PD‐L1 (r = 0.7434, p = 0.001), and phosphorylation of JAK1 (r = 0.7926, p < 0.001) and STAT3 (r = 0.8613, p < 0.001) in bladder cancer tissues." (PMID 37480214, 2023). "Based on the TCGA results, we decided to analyse expression and activation level of JAK1/2 and STAT3 in a panel of 10 different bladder cancer derived cell lines." (PMID 32046095, 2020). "Alterations in JAK1 were observed in 8% and in JAK2 in 15% of patients indicating, that these genes are frequently altered in bladder cancer." (PMID 32046095, 2020). "Our results from bladder cancer cells indicate that IL-20 induced activation of ERK1/2 and Jak1, Jak2, Jak3, Stat1, Stat2, and Stat5." (PMID 22962576, 2012). "We have also identified the activation of ERK1/2, p38MAPK, JNK, JAK1, JAK2, JAK3, Stat1, Stat2, and Stat3 in bladder cancer cells." (PMID 22962576, 2012). "The JAK/STAT pathway involves JAK1/2 and STAT1-6, with JAK1/2-STAT3 receiving the most attention because of its core regulatory role in malignant tumor progression, such as in hepatocellular, colorectal, cervical and bladder cancer." (PMID 38336839, 2024). "OPN, a substrate of Fam20C involved in cell differentiation, was overexpressed in bladder cancer tissues and OPN knockdown could suppress proliferation and invasion of human bladder cancer T24 cell via the JAK1/STAT1 pathway." (PMID 34988120, 2021). "Considering these findings, we explored targeting of the JAK1/2 and STAT3/5 proteins using specific small molecule inhibitors and combined these inhibitors with standard chemotherapy, inhibitors of cell cycle progression and oncolytic adenovirus in preclinical models of bladder cancer." (PMID 32046095, 2020).
inflammatory bowel disease (14 papers, 2016 to 2025). A spectrum of small and large bowel inflammatory diseases of unknown etiology. "For example, the literature supports that inhibition of janus kinase 1 (JAK1) improves inflammatory bowel disease; JAK1/3 inhibitors are a therapeutic modality for ankylosing spondylitis." (PMID 40231941, 2025). "Upadacitinib, a selective JAK1 inhibitor, has shown promise in treating inflammatory bowel disease, and there is growing evidence supporting its efficacy in sarcoidosis." (PMID 40351964, 2025). "The selective targeting of JAK1 is a cutting-edge and effective therapeutic strategy applicable to inflammatory bowel disease treatment." (PMID 40004077, 2025). "Similarly, the JAK1 inhibitors Filgotinib and Upadacitinib are used to treat inflammatory bowel disease." (PMID 37122731, 2023). "Filgotinib, a JAK1 inhibitor, was recently approved by the FDA to treat inflammatory bowel disease." (PMID 38170681, 2024).
liver fibrosis (14 papers, 2019 to 2025). "Here, we aim to determine the effect and underlying mechanism of JAK1/2 inhibition on liver fibrosis and hepatic stellate cells (HSCs) and further explore the therapeutic efficacy of Ruxolitinib, a JAK1/2 selective inhibitor, on preventing and reversing liver fibrosis in mice." (PMID 35382859, 2022). "Collectively, our results suggest that PZH exerts pharmacological effects on liver fibrosis by modulating the EGFR/JAK1/STAT3 signaling pathway." (PMID 41181146, 2025). "The findings reveal that PZH ameliorates liver fibrosis by inhibiting macrophage-mediated inflammation via blockade of the EGFR/JAK1/STAT3 signaling axis, providing a mechanistic foundation for its clinical application." (PMID 41181146, 2025). "Ruxolitinib, a small molecule that directly targets Janus kinase 1/2 and slows the progression of liver fibrosis, has, however, demonstrated promising anti-fibrotic benefits in both in vitro and in vivo tests." (PMID 40649803, 2025). "The effects of Ruxolitinib (JAK1/2 inhibitor) on liver fibrosis were studied in LX-2 cells and two progressive and reversible fibrosis animal models (carbon tetrachloride (CCl4), Thioacetamide (TAA))." (PMID 35382859, 2022). "Since the activation and proliferation of HSCs in the main trigger for liver fibrosis and subsequent liver disease, to investigate the role of JAK1 and JAK2 on HSCs, LX-2 cells were transfected with siJAK1, siJAK2, or both of them." (PMID 35382859, 2022). "In this study, we found that enhanced JAK1 and JAK2 expression were associated with liver fibrosis/cirrhosis and liver cancer." (PMID 35382859, 2022). "Our results suggest that the expression of JAK1 and JAK2 was associated with liver cancer progression and was also positively correlated with the severity of liver fibrosis." (PMID 35382859, 2022). "In brief, the current work showed that PZH may act as a therapeutic agent for liver fibrosis by inhibiting the EGFR/JAK1/STAT3 signaling axis and macrophage M1 polarization." (PMID 41181146, 2025). "While the EGFR/JAK1/STAT3 pathway is associated with fibrosis in various organs, its role in liver fibrosis remains unclear." (PMID 41181146, 2025). "For instance, a recent study showed that TGF-β could promote liver fibrosis by directly activating Janus kinase 1 (JAK1) and signal transducer and activator of transcription 3 (STAT3), with the assistance of the SMAD signaling pathways." (PMID 38766485, 2024). "Taken together, these results suggest that JAK1/2 promotes activation of HSCs and may be useful markers to monitor liver fibrosis and HCC development." (PMID 35382859, 2022). "Therefore, STAT3 and JAK1 are potential target proteins in HSCs for the treatment of liver fibrosis." (PMID 35517817, 2022). "In vitro studies then demonstrated that LS could inhibit the HSC viability, promote the HSC apoptosis, decrease the expression of liver fibrosis markers, and downregulate the JAK1/STAT3 signaling pathway." (PMID 35517817, 2022). "HSC-based in vitro experiments demonstrated that LS could inhibit the cell viability, promote the cell apoptosis, decrease the expression of liver fibrosis markers, as well as downregulate the JAK1/STAT3 signaling pathway." (PMID 35517817, 2022). "A previous study reported that STAT3 directly participated in the activation and transdifferentiation of HSC in response to TGFβ and subsequent hepatic fibrosis, it also showed that the JAK1/STAT3 signaling pathway played an important role in HSC activation and liver fibrosis." (PMID 35517817, 2022). "Further studies to explore the mechanism by primary HSCs and to investigate whether JAK1/2 inhibition prevents recurrence of HCC with the background of liver fibrosis in needed." (PMID 35382859, 2022). "The results showed that LS could inhibit the cell viability, promote the cell apoptosis, decrease the expression of liver fibrosis markers, and downregulate the JAK1/STAT3 signaling pathway." (PMID 35517817, 2022).
liver fibrosis (continued). "This activation triggers HSC transformation into myofibroblasts, inhibiting ECM degradation.Molecular docking simulations suggest that ginsenoside Rh2—a bioactive constituent of PZH—may attenuate hepatic fibrosis through modulation of the EGFR/JAK1/STAT3 signaling axis." (PMID 41181146, 2025). "Therefore, we further validated whether the JAK1/STAT3 signaling pathway was involved in the LS-mediated anti-liver-fibrosis process." (PMID 35517817, 2022). "Moreover, TGFβ can directly activate the JAK1/STAT3 axis in HSCs to induce liver fibrosis." (PMID 35517817, 2022). "JAK1/2 inhibition had similar actions on HSCs in a concentration-dependent model in vitro and obviously attenuated the progress of liver fibrosis, promoted its reversal, and improved the liver damage in different liver fibrosis mice model induced by CCl4 or TAA." (PMID 35382859, 2022). "Interestingly, this study showed that JAK1/2 expression was up-regulated in liver fibrosis and HCC, and further positively associated with liver cancer progression and the severity of liver fibrosis, indicating that JAK1/2 may take an action in liver fibrosis." (PMID 35382859, 2022). "Therefore, JAK1/2 may be considered as a potential marker of activated HSCs and therapeutic targets in the treatment of liver fibrosis." (PMID 35382859, 2022). "The recent identification of PZH’s modulation of the EGFR/JAK1/STAT3 pathway enhances its known inhibitory effects on the TGF-β1/Smad2 axis, thereby elucidating a multifaceted mechanism against hepatic fibrosis." (PMID 41181146, 2025). "In our experiments, PZH administration significantly reduced the expression of EGFR, JAK1, and STAT3 in liver tissues compared to liver fibrosis mice." (PMID 41181146, 2025). "Activation of the EGFR and JAK1/STAT3 signaling pathways has been shown to promote pro-inflammatory polarization in macrophages, thereby accelerating hepatic fibrosis through mechanisms such as inflammation regulation, oxidative stress, and apoptosis." (PMID 41181146, 2025). "More interestingly, we found that expression of JAK1 and JAK2 was positively correlated with the progression of liver cancer and the severity of liver fibrosis." (PMID 35382859, 2022). "We found that JAK1/2 expression was positively correlated with the progression of HCC in humans and the levels of liver fibrosis in mice." (PMID 35382859, 2022). "Immunohistochemistry staining of JAK1 and JAK2 were performed on liver tissue in mice with hepatic fibrosis and human liver tissue microarray of liver cirrhosis and liver cancer." (PMID 35382859, 2022). "We further analyzed the relationship between the expression of JAK1 and JAK2 and the degree of liver fibrosis in mice." (PMID 35382859, 2022). "In liver fibrosis, JAK1 is a constitutive TGFβRI-binding protein; thus, STAT3 is activated directly through JAK1 within minutes of TGFβ stimulation in a SMAD-independent manner." (PMID 34824210, 2021). "Of which, core targets (EGFR, STAT3, JAK1) all are enriched in cancer signaling pathways, given their high connectivity in the PPI network and established crosstalk in liver fibrosis, we hypothesized that PZH modulates the EGFR/JAK1/STAT3 signaling axis." (PMID 41181146, 2025). "However, the increased expression of serum EBI3 can promote the high expression of gp130 in HSCs, activating the JAK1/STAT3 pathway, which in turn inhibits the expression of ECM and leads to attenuated liver fibrosis." (PMID 37480105, 2023). "JAK1 and JAK2 have been implicated in fibrosis and cancer as a fibroblast-related marker; however, their role in liver fibrosis has not been elucidated." (PMID 35382859, 2022). "IPA of MYOC/CCL19 fibroblast gene expression correlating with the mRSS revealed several prominent pathways: senescence, hepatic fibrosis signaling, IL-6 signaling, STAT3 signaling, TGF-β signaling, protein ubiquitination, JAK/Stat signaling, and role of JAK1, JAK2 and TYK2 in interferon signaling." (PMID 35943798, 2022).
liver fibrosis (continued). "Our results suggested that LS could exert anti-liver-fibrosis effects by inhibiting the activation of HSCs, targeting JAK1 and STAT3, and regulating the JAK1/STAT3 signaling pathway." (PMID 35517817, 2022). "In addition, it has been reported that Asiatic acid can ameliorate CCl4-induced liver fibrosis in rats by regulating PI3K/AKT/mTOR, Bcl-2/Bax, Nrf2/ARE, NF-κB/IκBα and JAK1/STAT3 signaling pathways." (PMID 31467589, 2019). "Additionally, in the hepatic fibrosis mouse model, fibrotic liver tissues exhibited marked upregulation of EGFR, p-JAK1/JAK1, and p-STAT3/STAT3 protein expression (P < 0.01), accompanied by increased phosphorylation of JAK1 and STAT3 (P < 0.01)." (PMID 41181146, 2025). "In conclusion, JAK1/2 regulate the biological function of HSCs, highlighting its role in liver fibrosis and early prevention of HCC development and its inhibitor, Ruxolitinib, may be an effective drug for preventing and reversing liver fibrosis." (PMID 35382859, 2022). "Therefore, JAK1 and JAK2 might play a key role in the process of liver fibrogenesis, and its potential inhibitor, Ruxolitinib, may be clinically useful in preventing or treating liver fibrosis." (PMID 35382859, 2022). "However, the role of JAK1 and JAK2 in liver fibrosis remains unclear." (PMID 35382859, 2022).